CD68 (CD68 molecule)
Diseases named in the same sentence as CD68 in open-access papers (continued):
Sharing a sentence is not in itself a finding about the gene and the disease.
tumor (continued). "In particular, we found that the high content of TBs in the invasive frontin, frontout, and tumour core as well as the low number of CD68+ cells and high PD-L1 expression in the invasive frontout, are indicators of bad prognosis." (PMID 33915698, 2021). "As a result, the ER+ cancer sample was clustered with ER+ tumor cells (ESR1+, KRT18+, and KRT5−), KRT5+/EPCAM+ double-positive cells, cancer-associated fibroblasts (CAFs) (DCN+), macrophages (CD68+), KRT5+/EPCAM− cells, and endothelial cells (VWF+)." (PMID 34685653, 2021). "For instance, the M1, CD204M2, and CD68 macrophages have been considered to confer protective immunity against several factors in the tumor microenvironment of NSCLC." (PMID 34268011, 2021). "Of importance, in the tumor tissues derived from the Sh-Prune-1-4T1 implanted mice there was a reduction of the number of infiltrating M2-TAMs (i.e., CD68+." (PMID 33426510, 2021). "By contrast, histiocytic infiltration is much more significant, since the presence of high amounts of CD68-positive cells heavily influences the progression and the bad outcome of the tumours (p = .037)." (PMID 33769181, 2021). "Pembrolizumab anti- PD-1 monotherapy alone cannot induce an effective immunologic response in most GBM patients, probably owing to a scarcity of T cells within the tumor microenvironment and a CD68+ macrophage preponderance." (PMID 34071306, 2021). "CD68 (a pan-macrophage marker) was used to identify CLS-B in non-tumor-containing breast adipose tissue." (PMID 34066392, 2021). "The addition of tumor/CD68+ cellular clustering was necessary to elucidate the clinical impact of CD68+ TAM infiltration." (PMID 33882057, 2021). "Subgroup analysis in the hrHPV+ group (N = 43) showed that high infiltration rates of CD68+ and CD163+ cells in the PT tumor compartment were associated with lymph node (LN) metastasis (p = 0.031 and p = 0.026, respectively)." (PMID 34194435, 2021). "We see that the FoxP3+ (and to a lesser extent CD8+) cells support voids at larger radius than CD68+ cells in this tumor." (PMID 34625491, 2021). "Multiplex immunohistochemistry showed that PD-1H was detected in CD4 T cells, CD8 T cells, and CD68 macrophages of ESCC tumor tissues." (PMID 34950702, 2021). "Tumor-associated macrophages (TAMs, which can be labeled by CD68 as CD68+ M) are also a significant component of tumor-infiltrating immune cells." (PMID 33613757, 2021). "(C-D) PDIA3 expression in TAM and co-localization with the pan-macrophage marker CD68 as detected by immunofluorescence of tumor tissue sections from tumor-bearing mice administered iv with anti-PDIA3 antibody (C) or CSSTRESAC-phage (D)." (PMID 34060472, 2021). "Immunohistochemistry revealed that, in CXCL1+TNBCs, the cellular sources of CXCL1 included, in addition to CD133+BCSCs, tumor infiltrating immune cells, such as CD68+ macrophages, and the vast majority of BC cells." (PMID 34195201, 2021). "CD68+ TAMs, which are thought to be partly derived from TAM1s are thought to be involved in effective human anti-tumor immunity." (PMID 34089486, 2021). "We next evaluated the association between PDCD4 expression and density of tumor-infiltrating lymphocytes as measured by CD3 (for T cells) or CD20 (for B cells) positivity, and macrophages as measured by CD68 positivity." (PMID 33801444, 2021). "The weight of gender, tumor diameter, PD-L1, and CD68+ macrophages were relatively low compared to other indicators." (PMID 34992605, 2021). "CD68 appeared to be the most applicable immune marker to stratify chemotherapy outcomes in patients with BCa categorized by nodal stage and tumor stage." (PMID 33467469, 2021). "Macrophages (CD68+F4/80+) infiltrating the tumor were significantly reduced in tumors of IRF3KO and IRF3KO-LRT group compared to WT group (p = 0.031 and 0.002, respectively)." (PMID 34768716, 2021).
tumor (continued). "VISTA expression was positively related with tumor-infiltrating CD68+ macrophages, CD3+ T cells, CD19+ B cells, CD4+ T-helper cells, and CD8+ cytotoxic T cells." (PMID 33237432, 2021). "Some tumor cells were positive for CD68, smooth muscle actin, vimentin and epidermal growth factor receptor." (PMID 33731032, 2021). "Patients with a favorable response following treatment with PD-L1 antibodies have an influx of CD68+ macrophages and other immune cells into the tumor microenvironment." (PMID 34359704, 2021). "After stratifying for both cell density and cell clustering, patients with high CD68+ density and high tumor/CD68+ clustering were found to have significantly worse OS (HR = 8.50, 95%CI 1.97–36.7, p = 0.004)." (PMID 33882057, 2021). "In tumors with a low CD8 + T-cells infiltrations, multiple immunofluorescence further revealed a low infiltration of NK (CD56 + ) cells and macrophages (CD68 + /HLA-DR + ) in the tumor stroma." (PMID 34489456, 2021). "Stromal CD20+/CD68+ and CD20+/CD163+ ratios were significantly and consistently associated with T classification, tumor grade, and second primary tumors." (PMID 33494389, 2021). "The immunohistochemical markers CD68 and CD163 for the detection of tumor-associated macrophages are widely used." (PMID 33530441, 2021). "Overall, NACT was associated with significant increases in anti-tumor CD8+, CD3+ TILs, and CD68+ macrophages and had a more variable impact on suppressive FOXP3+ TILs and CD163+ macrophages." (PMID 32852603, 2021). "The primary objective is to determine DNA methylation and DNA repair levels before, and immediately after treatment; quantify immune-response markers (PDL-1, PD-1, CD4/CD8, and CD68) in blood, tumor and microenvironment before treatment and after 2 cycles." (PMID 32569203, 2020). "These phenotypes were due to increased proliferation of both tumor cells and macrophages (Ki67+CD68− and Ki67+CD68+ cells, respectively) (Ctrl+TAM vs Ctrl)." (PMID 32286255, 2020). "Previous investigations have suggested there is an increase in the density of CD68+ macrophages in advanced tumour stages." (PMID 32843682, 2020). "Tumours with high IL-34 plus high CD68+-TAMs had the best prognosis, tumours with high or low IL-34 plus low or high CD68+-TAMs had mid-level prognosis and tumours with low IL-34 plus low CD68+-TAMs had the worst prognosis in GC patients." (PMID 32765828, 2020). "A number of studies showed that the increase in TAM number, defined by the expression of pan-macrophage marker CD68 correlated with a greater degree of severity of the tumor process." (PMID 33194645, 2020). "We investigated the expression of PD-1, PD-L1, CD8+ T cells, and CD68+ macrophages in paired tumor and adjacent normal tissues from 322 ICC patients using tyramide signal amplification (TSA)-based multiplexed immunohistochemistry." (PMID 33228682, 2020). "With regard to macrophage polarity, increasing statin dosage showed a statistically significant association with diminished CD68+/CD163+ staining in parenchymal and stromal areas within in situ tumor regions." (PMID 32190817, 2020). "The flow cytometry results showed that the percentage of M2 macrophages (CD163+/CD68+) was increased when M0 macrophages were co-cultured with FOXO1(+) tumor cells." (PMID 33052231, 2020). "Tumour-infiltrating FOXP3 + lymphocytes and CD68 + macrophages were both predominant in tumours with high SLCs and to a lesser extent in those tumours with high SLC1A5 expression (p < 0.0001)." (PMID 31819174, 2020). "CD68 is a widely used macrophage marker that can be used to assess the extent of macrophage infiltration in tumor tissue." (PMID 32536823, 2020). "Association between infiltration of CD68+ macrophages and EGFR-status was demonstrated in study of 105 surgically resected tumor samples (50 EGFR mutated and 55 EGFR wild-type)." (PMID 33194645, 2020).
tumor (continued). "For example, the high number of CD68+/COX-2 TAMs in the tumor stroma (TS) and high number of COX-2/CD163 in both tumor nest (TN) and TS were observed in tumors of patients with poor survival that was demonstrated by using multiplex immunofluorescence." (PMID 33194645, 2020). "Another study on 35 PitNETs, including 18 somatotroph tumours, showed a positive correlation between the number of infiltrating CD68+ macrophages and tumour size and invasiveness." (PMID 31875303, 2020). "The findings showed that patients with the pathologic complete response (pCR) were shown to have higher PD‐L1 expression in tumor, stromal and CD68 (macrophage) compartments compared to patients with non‐pCR." (PMID 33251010, 2020). "Because both M1 and M2 macrophages are CD68+ TAMs, and each type has an opposite effect on tumours, defining the effects of each of the two kinds of macrophages on RFS is challenging." (PMID 32076456, 2020). "Our results indicate that KMP01D promotes apoptosis of CD68+ cells in PBMCs and tumor-derived cells as demonstrated by our TUNEL assay." (PMID 32425932, 2020). "IP2 includes markers for T cells (CD3), cytotoxic T cells (CD8), macrophages (CD68), tumor/epithelial cells (CK), and two immune checkpoint molecules (PD-1 and PD-L1)." (PMID 33590360, 2020). "The PCNs increased the number of cytotoxic CD8+ T lymphocytes and CD68+iNOS+ M1-like macrophages, induced minimal changes in CD4+ T lymphocytes, and decreased CD68+/Arg-1+ M2-like macrophages in tumor tissues." (PMID 32928251, 2020). "IL-34 and M-CSF were decreased > 40% and > 95%, respectively, in GC compared to tumour adjacent gastric tissues (p < 0.05), whereas CD68+-TAMs were increased 5.5 fold (p < 0.05)." (PMID 32765828, 2020). "Next, we examined expression of macrophage marker CD68 in the GC tissue array and found that CD68 was also highly expressed in tumor tissues compared to normal mucosa, suggesting that there are more macrophages infiltrated in tumors than in normal tissues." (PMID 31903134, 2020). "The tumor cells were intermingled with the fibrous stroma and normal breast parenchyma and showed positive immunoreaction to S-100, CD68, and neuron-specific enolase." (PMID 33217851, 2020). "Infiltration of the tumor microenvironment by CD68+ and CD163+ macrophages, Treg and CD4+ T cells (especially with Th2 phenotype), and high CD4/CD8 ratio is associated to the emergence of resistance to conventional therapy, and a worse prognosis." (PMID 34191173, 2020). "With respect to the immune profile of the mUM, we confirm our previous results that the main “reactive inflammatory” cell within these metastatic tumours is the M2 macrophage with an expression of CD68, CD163, and CD4." (PMID 33008022, 2020). "Regarding to the involvement of tumor-associated macrophage (TAM) in the microenvironment, we monitored the expressions of TAM markers including CD68 and CD163 as well as angiogenesis marker CD31 in xenograft slice." (PMID 32327633, 2020). "Instead, the melanin-laden cells were positive for the macrophage marker CD68, revealing that the “dormant tumour” was in fact a large group of melanophages." (PMID 32957691, 2020). "Lower number of CD68+ cells in tumor border was also found in patients where tumor cell invaded the blood circulation, lymph vessels or were characterized by perineural invasion and lower grade of inflammatory infiltration." (PMID 33194645, 2020). "High CD68+ TAM infiltration in tumor tissue of 123 patients with metastatic CRC decreased the efficacy of bevacizumab plus FOLFIRI scheme (folinic acid, 5-fluorouracil, irinotecan) of chemotherapy." (PMID 33194645, 2020). "PD1, CD3, CD8 and CD68 expression was evaluated by immunohistochemistry in tumor infiltrating immune cells, while PD-L1 expression in the tumor microenvironment was assessed." (PMID 31996725, 2020).
tumor (continued). "CD20 expression and CD68 + TAM numbers were assessed in representative tumor tissues obtained from 81 cHL patients using flowcytometry (FCM), immunohistochemistry (IHC), and Rt-PCR techniques." (PMID 32019558, 2020). "Tumor size, degree of tumor invasion, lymphatic metastasis and pathological grading correlate with high levels of CD68 and CCL5." (PMID 32630699, 2020). "In a small cohort of patients (seven patients, USA) who received paclitaxel-based NAC the amount of CD68+ TAMs in the tumor after NAC was higher than in biopsy specimens obtained before NAC." (PMID 33194645, 2020). "We compared the methylation status of the NT5E gene according to the expression of inflammatory markers including TNF-α, IL-4, NF-κB p50, CD4+, and CD8+ T cells, CD68+ macrophages, intratumoral and peritumoral inflammation in tumor tissues." (PMID 33198064, 2020). "Multiplex immunofluorescent staining of tumor samples from NSCLC Swedish patients demonstrated the co-localization of CD68, CD163, and MARCO." (PMID 33194645, 2020). "CD8+ T cells and CD68+ macrophages were found in significantly greater numbers in HPV+ OPSCC tumours." (PMID 31806878, 2020). "Accordingly, in a previous study, we showed that the proportion of CD68+ cells in the tumor increased with the tumor hypoxic status." (PMID 33266255, 2020). "The mean number of CD68+ macrophages in the tumor nests and the surrounding stroma was 51.11 ± 45.08 per mm2 (range: 0.00 to 194.00) and 122.72 ± 82.49 per mm2 (range: 9.67 to 488.67), respectively." (PMID 32630659, 2020). "Post hoc exploratory analyses included next-generation sequencing to assess tumor mutational burden (TMB), and immunostaining for CD8+ T-cells and CD68+ macrophages." (PMID 32823925, 2020). "Upregulation of tumor promoting genes in the PD-L1 positive group were notable for CD68, MED19 and CD46." (PMID 33415077, 2020). "An analysis of tumor stroma was done using CD68 for macrophages, iNOS for type 1 macrophages (M1), CD206 and CD163 for type 2 macrophages (M2), CD3 for T-cells, CD8 for cytotoxic T-cells and FoxP3 for Treg." (PMID 32933105, 2020). "Immunohistochemistry results showed markedly increased CD68 expression in tumour tissues relative to paracancerous tissues, and elevated CD68 expression was also observed in response to high ER stress as compared to low ER stress." (PMID 32672418, 2020). "The tumor tissues presenting VAP-1/CD68, VAP-1/iNOS, and VAP-1/CD163 coexpression were detected in 47 (43.52%), 29 (26.85%), and 49 (45.37%) specimens respectively." (PMID 32349342, 2020). "PD-L1 expression positively correlated with high expression levels of tumor promoting genes such as CD68, ADAM12, FXYD5, S100A11, CD46, and MED19 (and ST1D)." (PMID 33415077, 2020). "RNA profiling of microenvironment-related genes revealed increased expression of markers for TAMs and resident microglia (Aif1, Itgam, Cd68 and Cx3cl1), and macrophage M1/M2 polarisation (Cd80 vs. Cd163) in knockdown tumours." (PMID 33339831, 2020). "Increase in the amount of CD68+ TAMs within tumor tissues of pre-treated patients compared to the untreated group was demonstrated." (PMID 33194645, 2020). "The immunohistochemistry results revealed that there were PD-1 and CD68 double positive cells (PD-1+ macrophages) and PD-1+CD68− cells, which were likely to be tumor-infiltrating lymphocytes, in GC tissues." (PMID 32131763, 2020). "In squamous cell carcinomas (SCC), recent studies found a positive correlation between CD68+ macrophages (both M1 and M2 phenotypes) and tumor progression in cervical cancers and oral SCC." (PMID 32635549, 2020). "Lastly, a recent paper shows IFITM3 is correlated with the inhibitory immune checkpoint receptors PD-L1, B7-H4, VISTA, IDO, and the tumor associated macrophage markers CD68, CD163, and CD206, which are associated with tumor immunosuppression." (PMID 33364194, 2020). "CD68+ macrophages were also only present in the tumor stroma and correlated with age of the patient and tumor size." (PMID 33377644, 2020).
tumor (continued). "Similar analyses performed on PD-1+ and CD68+ tumor-infiltrating cells showed that patients with many PD-1+ and CD68+ cells had a longer overall survival after IHP." (PMID 33344043, 2020). "Traditionally, CD68 is exploited as a valuable cytochemical marker to immunostain monocyte/macrophages in the histochemical analysis of inflamed tissues, tumor tissues, and other immunohistopathological applications." (PMID 33061855, 2020). "We have also demonstrated that CD68+ macrophages were strongly recruited during the tumor progression from the peri-tumoral tumor free epithelia until dysplasia and carcinomas." (PMID 32344813, 2020). "Next, we plotted the expression of the general macrophage marker CD68 and the tumor-associated macrophage marker CD163 versus F2R in tumor-only datasets." (PMID 32809114, 2020). "Co-staining of PD-L1, MARCO, and CD68 revealed MARCO+ TAMs are in direct contact with PD-L1+ tumor cells and demonstrated co-localization of MARCO and PD-L1 in TAMs." (PMID 33194645, 2020). "The number of CD68+ cells was positively correlated with tumor size and Knosp classification grade for tumor invasiveness." (PMID 33362722, 2020). "High density of CD68+ macrophages correlated with smaller tumor size (P = 0.003) and tumor number (P = 0.014)." (PMID 33228682, 2020). "We found relative expression of CD14 and CD68 to be downregulated in PBMCs and tumor-derived cells following incubation with KMP01D." (PMID 32425932, 2020). "One study indicated that the number of CD68+ macrophages was positively correlated with tumor size and Knosp classification grade for tumor invasiveness." (PMID 33362722, 2020). "IP2 identifies 4 different cell types: CD3+CD8- T cells, CD3+CD8+ cytotoxic T cells, CD68+ macrophages, and CK+ epithelial/tumor cells." (PMID 33590360, 2020). "Multiplexing enabled PD-L1+/CD68+ macrophages to be readily identified within PD-L1+/cytokeratin+ or PD-L1-/cytokeratin+ tumor nests." (PMID 32365629, 2020). "The tumor cells expressed macrophage-related F4/80, CD68, and CD204 as well as cytoplasmic B220 and μ-/κ-chains; in addition, these cells exhibited phagocytic activity." (PMID 31947626, 2020). "After sacrifice, we proceeded to verify macrophage infiltration in formalin-fixed tumor samples from the restraint stress model through CD68 immunohistochemical staining (p < 0.01)." (PMID 32962103, 2020). "Tumor biopsies with high tumor vascular ANGPT2 expression showed an increase in CD68+ and CD163+ macrophages after Ipilimumab or Ipi-bev treatment." (PMID 32793228, 2020). "Associations among fecal occult blood test (FOBT) result, CD68, IL-6, and TNF-α expression in tumor cells." (PMID 33643891, 2020). "It was also favorable for the patients to have a high amount of tumor-infiltrating CD68+ macrophages." (PMID 33344043, 2020). "Due to the occasional expression of CD68 in tumor epithelium cells, the total number of ieTAMs was sometimes overestimated." (PMID 32824692, 2020). "Strong correlation of PU.1 primarily with CD68 suggests possible usage of this marker as a general macrophage marker for tumor stroma." (PMID 32884895, 2020). "Findings: We identified the heterogeneity underlying tumor immune signature in OSA, and found CD4+ T cells and macrophage markers CD4/IFNGR2/CD68 to be feasible prognostic factors, exerting significantly positive correlation with each other." (PMID 32850346, 2020). "The total number of CD68+ cells was increased in tumor tissue when compared to the adjacent normal mucosa." (PMID 33371444, 2020). "Although several studies have shown the prognostic value of tumor-associated macrophage infiltrates in CRC, we were not able to demonstrate an independent prognostic value of TME CD68+ cell densities." (PMID 33050344, 2020). "Immunofluorescence results demonstrated the co‐localization of PD‐L1 and CD68+ macrophage in tumour stroma of the high ER stress group." (PMID 32672418, 2020).